TIMP2 (TIMP metallopeptidase inhibitor 2)
Diseases named in the same sentence as TIMP2 in open-access papers (continued):
Sharing a sentence is not in itself a finding about the gene and the disease.
keratoconus (3 papers, 2022 to 2025). A degenerative, structural disorder of the eye, characterized by a cone-shaped protrusion of the cornea. "Statistical univariate analysis of TIMP-2 for its usefulness as a potential predictor of keratoconus showed its sensitivity of 88% and specificity of 90%." (PMID 38398480, 2024). "Due to the very small number of studies on TIMP-2 in keratoconus, it is difficult to precisely determine its significance in the pathophysiology of this disease." (PMID 38398480, 2024). "The analysis of individual TIMPs in terms of their usefulness as potential predictors of keratoconus showed high results of diagnostic sensitivity and specificity for all TIMPs, in particular for TIMP-1 and TIMP-2." (PMID 38398480, 2024). "In the presented study, the median serum TIMP-2 concentration in keratoconus patients was 1.5 times higher than in the control group." (PMID 38398480, 2024). "High diagnostic sensitivity and specificity values of TIMP-1 and TIMP-2 and high diagnostic specificity values of TIMP-3 and TIMP-4 in relation to keratoconus were demonstrated, which confirms their strong role in the etiopathogenesis of this disease, especially when they all interact together." (PMID 38398480, 2024). "TIMP-2 may therefore be a predictive factor of the tendency toward scar formation.Further research would be needed in this direction, especially in the context of keratoconus and the correlation of TIMP-2 concentration in the corneal tissue and its healing after a corneal cross-linking procedure." (PMID 38398480, 2024). "Multiple studies do show a consistent relative decrease in TIMP levels, including TIMP-2, compared to MMP-2 levels in corneas and keratocyte cultures derived from keratoconus patients, suggesting upregulated MMP-2 plays a role in keratoconus." (PMID 39883547, 2025). "TIMP-1, TIMP-2, TIMP-3, and TIMP-4 values were analyzed for their usefulness as potential predictors of keratoconus." (PMID 38398480, 2024). "The aim of the study was to determine the concentration of the TIMPs TIMP-1, TIMP-2, TIMP-3, and TIMP-4 in the blood serum samples of patients with keratoconus compared to the control group." (PMID 38398480, 2024). "–56 This relationship suggests that WST-D/NIR treatment might have a targeted effect on the pathways involved in keratoconus, by reversing the dysregulation of MMP-2 in keratoconus by the upregulation of TIMP-2." (PMID 39883547, 2025). "Statistical univariate analysis of TIMP-3 for its usefulness as a potential predictor of keratoconus showed itssensitivity of 54% and specificity of almost 90% which probably indicates its smaller importance in the etiopathogenesis of keratoconus compared to TIMP-1 and TIMP-2." (PMID 38398480, 2024).
kidney injury (3 papers, 2018 to 2024). Trauma to the kidney. "Our study proves the diagnostic utility of urinary [TIMP-2]·[IGFBP7] in a diverse patient population after a defined initial event of kidney injury and standardized ICU management." (PMID 29751827, 2018). "In this context, a unique [TIMP-2]∙[IGFBP7] measurement may not able to mirror the complex dynamic of kidney injury, because this accuracy might progressively decrease over time." (PMID 31712687, 2019).
leiomyosarcoma (3 papers, 2013 to 2023). An uncommon, aggressive malignant smooth muscle neoplasm, usually occurring in post-menopausal women. "In addition, TIMP2 is also expressed at relatively low levels in leiomyosarcomas." (PMID 24398114, 2014). "As anticipated, a significant positive correlation was found between the secretion of u-PA and MMP-9 and a significant negative correlation was found between MMP-9 and TIMP-2 and between u-PA and TIMP-2 secretion by leiomyosarcoma SK-UT-1 cell line." (PMID 23661254, 2013).
Miscarriage (3 papers, 2010 to 2025). A pregnancy that ends at a stage in which the fetus is incapable of surviving on its own, defined as the spontaneous loss of a fetus before the 22th week of pregnancy. "Three genes, OFD1, TRAPPC2 and TIMP2 out of 14 selected for expression analysis had altered mRNA and protein expression in cultured miscarriage chorionic villi cells." (PMID 25674159, 2015). "TIMP2 is the third gene that showed altered expression in miscarriages and is known to inhibit matrix metaloproteases (MMPs), which degrade extra cellular matrix (ECM), and have a critical role in tissue remodelling and angiogenesis in placenta/endometrium." (PMID 25674159, 2015). "Excessive TIMP2 expression disrupts the fine-tuned MMP2/TIMP2 balance, leading to abnormal ECM degradation in the endometrium, which interferes with embryo implantation and normal placental development, potentially causing spontaneous miscarriage." (PMID 40151207, 2025). "The miscarriage rates in the index pregnancy in our series were so low that we could not determine the temporal relationship, if any, between serum RLX-2 and TIMP-2 levels and subsequent miscarriage." (PMID 20565712, 2010).
papillary thyroid cancer (3 papers, 2022 to 2025). "On the other hand, circLIFR can sponge miR-429 to increase the expression of tissue inhibitor of metalloproteinase 2 (TIMP2) in papillary thyroid cancer, a crucial regulator of EMT and cancer metastases." (PMID 39736850, 2025). "Recent research indicated that Angiopoietin-1 played a role in lymph node metastasis and invasiveness of papillary thyroid carcinoma TIMPs, which comprise a family of four protease inhibitors: TIMP1, TIMP2, TIMP3, and TIMP4." (PMID 36672532, 2022).
pituitary adenomas (3 papers, 2016 to 2022). "The objective of this meta-analysis was to assess the relationship between expression of MMP-9, MMP-2, and TIMP-2 and invasion of pituitary adenomas." (PMID 27310993, 2016). "This retrospective cohort study aimed to study the expression of tumoral biomarkers (CTSK, MMP9, MMP2, TIMP2, and PTTG1) and evaluate their clinical significance in non-functioning pituitary adenomas (NFPAs) with different invasion patterns." (PMID 36052250, 2022).
renal dysfunction (3 papers, 2017 to 2025). "MM patients exhibited renal dysfunction (low eGFR, high creatinine), hypoalbuminemia, elevated β2-microglobulin, high LDH, increased plasma cell percentage, and elevated serum amylase, along with elevated urinary biomarkers IGFBP-7 and TIMP-2, reflecting systemic and renal involvement." (PMID 40369504, 2025).
Renal insufficiency (3 papers, 2013 to 2024). A reduction in the level of performance of the kidneys in areas of function comprising the concentration of urine, removal of wastes, the maintenance of electrolyte balance, homeostasis of blood pressure, and calcium metabolism. "U IGFBP-7/creatinine ratio, U TIMP2/creatinine ratio, and serum transgelin levels were higher in patients with MM than healthy controls, and predicted renal insufficiency in MM." (PMID 38708150, 2024). "ROC curve analysis demonstrated that U IGFBP-7/creatinine ratio, U TIMP2/creatinine ratio, and serum transgelin had predictive value for renal insufficiency (eGFR < 60mL/min/1.73 m2)." (PMID 38708150, 2024). "In the current study, TIMP-2 rise was positively correlated with history of renal insufficiency and heart rate and negatively with body mass index." (PMID 24156746, 2013). "Additionally, changes in VEGF were correlated to previous thrombolytic therapy; while changes in TIMP-2 were related to history of renal insufficiency, baseline heart rate and BMI." (PMID 24156746, 2013).
retinopathy of prematurity (3 papers, 2017 to 2023). A bilateral retinopathy characterized by neovascularization, scarring, retinal detachment, and eventually blindness. "Associations between TIMP-2 gene polymorphisms and the risk of retinopathy of prematurity (ROP) were examined." (PMID 36430677, 2022). "Levels of THBS1, MMP8, MMP9, MMP25, TIMP2 and TIMP3 increased as severity of BPD and retinopathy of prematurity (ROP) increased, whereas ETS1, LEF1 and SPOCK2 exhibited the opposite trend." (PMID 28103583, 2017).
steatosis (3 papers, 2023 to 2024). Increased lipid within the cytoplasm of cells. "Mechanistically, miR-483-5p targets Peroxisome-proliferator-activated receptor alpha (PPARα) and Tissue inhibitor of metalloproteinases 2 (TIMP2) gene expression leading to the suppression of steatosis and fibrosis." (PMID 37958352, 2023). "Downregulation of miR-483-5p links HCC, NAFLD, and AFLD, inducing the upregulation of PPARα and TIMP2 responsible for the increased steatosis and fibrosis and HCC progression as well (brown arrow)." (PMID 37958352, 2023). "Although ETs do not regulate cell steatosis but cause inflammation in HepaRG and HCC cells, here, we further investigated the effect of ETs (single exposure and in combination) on the expression of cell fibrosis markers such as AST, FGF-23, Cyt-7, p21, TGF-β, TIMP2, and MMP2." (PMID 39771071, 2024).
systemic sclerosis (3 papers, 2007 to 2020). A chronic disorder, possibly autoimmune, marked by excessive production of collagen which results in hardening and thickening of body tissues. "Based on these results, we speculate that MMP-9, MMP-2, TIMP-2, and VEGF/sVEGFR-2 may play an important role in ischemic retinal degeneration or retinal reorganization in systemic sclerosis." (PMID 33218057, 2020).
ulcer (3 papers, 2010 to 2022). "As such, this study surveyed if the H. pylori dupA genotype and certain SNP genotypes of MMP-3, MMP-7, MMP-9, TIMP-1, and TIMP-2 predispose H. pylori-infected Taiwanese patients to ulcer risks." (PMID 20707923, 2010). "This study investigated if the H. pylori dupA genotype and certain host single nucleotide polymorphisms (SNPs) of matrix metalloproteinases (MMPs) and their inhibitors (TIMPs), including MMP-3, MMP-7, MMP-9, TIMP-1 and TIMP-2, might correlate with ulcer risk of H. pylori-infected Taiwanese patients." (PMID 20707923, 2010). "Mmp9 is a main effector of the ulcer response, and as shown in the PrU network, it corresponds to an increase of Timp1 and Timp2, the two main inhibitors of metalloproteinases." (PMID 35386010, 2022). "A decrease in the gene expression of laminar TIMP-2 was also found in horses with OF-induced laminitis and dairy cows with sole ulcer." (PMID 33426020, 2020).
ulcerative colitis (3 papers, 2008 to 2023). An inflammatory bowel disease involving the mucosal surface of the large intestine and rectum. "The aim of our study was to evaluate the expression of MMP-2, MMP-7, MMP-9, TIMP-1, and TIMP-2 in ulcerative colitis and Crohn's disease." (PMID 27034654, 2016). "TIMP-1, TIMP-2 and TIMP-4 serum levels were determined in 53 patients with ulcerative colitis (UC), 52 patients with Crohn's disease (CD) and 50 HC, by means of commercially available enzyme-linked immunosorbent assays." (PMID 19036126, 2008).
viral infection (3 papers, 2015 to 2025). "The lack of renal TIMP-2, IGFBP7 and NGAL upregulation is not likely to be directly related to viral infection." (PMID 34112226, 2021).
acute respiratory distress syndrome (2 papers, 2024 to 2025). Progressive and life-threatening pulmonary distress in the absence of an underlying pulmonary condition, usually following major trauma or surgery. "Furthermore, TIMP2*IGFBP7 was characterized by a high diagnostic value of AKI in patients with SARS-CoV2-associated acute respiratory distress syndrome." (PMID 39596140, 2024).
ameloblastoma (2 papers, 2008 to 2014). The most common odontogenic tumor, arising from the epithelial component of the embryonic tooth and usually affecting the molar-ramus region of the mandible or maxilla. "Transfecting human TIMP2 cDNA into human ameloblastoma cells caused xenograft growth inhibition in nude mice." (PMID 24475196, 2014). "The invasion assay showed that the ability of ameloblastoma cells to invade the lower surface of the filter through the Matrigel was significantly inhibited in both MMP-2 knockdown or TIMP-2 overexpression cells compared to the control cultures." (PMID 18588710, 2008). "Further, zymography and reverse gelatin zymography assays revealed that pcDNA-TIMP-2 transfection decreased MMP-2 activity and increased TIMP-2 activity in ameloblastoma cells." (PMID 18588710, 2008). "Plasmids containing either MMP-2 siRNA or tissue inhibitor of metalloproteinase-2 (TIMP-2) cDNA were created and subsequently transfected into primary ameloblastoma cells." (PMID 18588710, 2008). "Analysis of the effect of MMP-2 siRNA or TIMP-2 overexpression on ameloblastoma cell invasion." (PMID 18588710, 2008). "TIMP-2 overexpression inhibited MMP-2 activity in ameloblastoma cells." (PMID 18588710, 2008). "This outcome suggested that TIMP-2 might suppress invasiveness in ameloblastomas in humans." (PMID 18588710, 2008). "Both MMP-2 siRNA and TIMP-2 overexpression inhibited MMP-2 activity and the in vitro invasiveness of ameloblastoma." (PMID 18588710, 2008). "This was accomplished using an MMP-2 gene knockdown approach or TIMP-2 overexpression and subsequently detecting the relationship between MMP-2 activity and the local invasiveness of ameloblastoma cells." (PMID 18588710, 2008). "To investigate whether inhibition of MMP-2 activity will suppress the invasiveness of ameloblastoma cells, we knocked down MMP-2 by RNA interference or overexpressed TIMP-2." (PMID 18588710, 2008). "Previous studies have shown that ameloblastomas have an elevated expression of MMP-2, MMP-9, and vascular endothelial growth factor (VEGF), and are void of or have an abnormal expression of E-cadherin and TIMP-2." (PMID 18588710, 2008). "In summary, these data indicate that siRNA targeting of MMP-2 mRNA or TIMP-2 overxpression using a plasmid-based system effectively inhibited the activity of MMP-2 in ameloblastoma cells, which subsequently resulted in reduced ameloblastoma cell invasiveness in vitro." (PMID 18588710, 2008).
anemia (2 papers, 2023 to 2025). A reduction in the number of red blood cells, the amount of hemoglobin, and/or the volume of packed red blood cells. "Furthermore, both biomarkers showed significant negative correlations with hemoglobin (r = −0.425, p = 0.002 for IGFBP-7; r = −0.463, p = 0.001 for TIMP-2), reflecting their association with anemia." (PMID 40369504, 2025). "FKN induces the secretion of the receptivity-related cytokines at anemia, which may improve endometrium receptivity via the CX3CR1 and the regulation of the NFκB pathway and by regulating activin, follistatin, and BMP2, as well as PR, SOX-17, PTGER2, and TIMP2." (PMID 37175630, 2023).
Arthritis (2 papers, 2005 to 2023). Inflammation of a joint. "The reverse pattern was observed for TIMP-2, an inhibitor of the MMPs family involved in diseases such as arthritis and metastasis." (PMID 38045809, 2023). "The expression of TIMP mRNA was determined in WT controls and p47phox-/- mice: TIMP-1 and TIMP-2 were moderately expressed after the induction of arthritis in both groups." (PMID 15987491, 2005).
bladder tumour (2 papers, 2004 to 2006). "Using RT–PCR, invasive bladder tumour samples were found to have higher expression of MMP2 and TIMP2 compared to superficial tumours, and high levels of MMP2, TIMP2 and MT1-MMP were associated with decreased patient survival." (PMID 15083203, 2004). "The authors concluded that MMP2 and TIMP2 contribute to bladder tumour invasiveness and therefore might be useful prognostic markers in the future." (PMID 16901349, 2006).
Cerebral ischemia (2 papers, 2022 to 2024). Restriction of arterial blood supply to the brain associated with insufficient oxygenation to support the metabolic requirements of the tissue. "The differential expression of IGF-2, TIMP-2, VEGFA, and bFGF observed in our study highlights the complex nature of the biological response to cerebral ischemia and the potential influence of therapeutic interventions." (PMID 38178130, 2024).
cervical squamous cell carcinoma (2 papers, 2010 to 2021). A squamous cell carcinoma arising from the cervical epithelium. "We found in this study that squamous cervical cancer patients had significantly lower TIMP-2 levels compared to healthy controls." (PMID 20671952, 2010). "In research on tissue of uterus obtained during hysterectomy in patients with cervical squamous cell carcinoma, the expression of membrane-bound matrix metalloproteinase MT1-MMP (MMP-14), its tissue inhibitor TIMP-2, and its activator proMMP-14 furin was investigated." (PMID 34830452, 2021). "Low TIMP-2 levels in the blood of squamous cervical cancer patients could indicate more activated MMP-2 and therefore higher usage of TIMP-2, or alternatively, the lower levels could be due to lower production of TIMP-2, leading to less inhibition of MMP-2 activity." (PMID 20671952, 2010).
clear cell renal cell carcinoma (2 papers, 2013 to 2022). "This study assessed the expression and clinical significance of matrix metalloproteinase 7 (MMP-7) and tissue inhibitor of matrix metalloproteinases 2 (TIMP-2) in human clear cell renal cell carcinoma (CCRCC) by tissue microarray, immunohistochemistry and RT-PCR analysis." (PMID 23408109, 2013).
coronary atherosclerosis (2 papers, 2021 to 2024). Atherosclerosis of the coronary vasculature. "MMP-9 and TIMP-2 were also found to be elevated in plasma patients with premature coronary atherosclerosis, emphasizing the significance of these biomarkers in assessing coronary vascular health." (PMID 39195176, 2024). "Another author found that patients with CAD had higher MMP‐9 and TIMP‐1 plasma levels but a lower TIMP‐2 level, also both increased MMP‐9 and TIMP‐ 1 plasma levels in premature coronary atherosclerosis patients, but with lower MMP‐3 and TIMP‐2 levels." (PMID 33381894, 2021).
disc degeneration (2 papers, 2023 to 2024). "The results of our study showed an increased expression of MMP-2 and concentration of TIMP-2 in DH compared with its levels in FBSS patients, which can be related to the early phase of process of disc degeneration." (PMID 37799188, 2023). "Although these catabolic factors were counteracted by even higher and increasing expression levels of their natural endogeneous inhibitors such as TIMP-1, TIMP-2, TIMP-3 and TIMP-4, we recoded declining levels of aggrecan and collagen II with increased severity of disc degeneration." (PMID 39286594, 2024).